CRP (C-reactive protein)
Diseases named in the same sentence as CRP in open-access papers (continued):
Sharing a sentence is not in itself a finding about the gene and the disease.
delirium (continued). "We set out to compare the role of blood concentration of homocysteine versus CRP in predicting postoperative delirium in patients." (PMID 36212043, 2022). "The delirium group needed longer administration of sedatives and longer ICU stay and showed higher CRP value and lower renal function but similar cardiopulmonary function before discharge from our hospital compared with the non-delirium group." (PMID 35962209, 2022). "There is little evidence in the literature on the clinical use of any delirium biomarkers, though some markers such as S-100 beta, insulin-like growth factor-1, cortisol and C-reactive protein (CRP) have shown some promising results." (PMID 36013306, 2022). "Despite these limitations, to the best of our knowledge, this is the first study to evaluate NLR and CRP in pre- and post-delirium onset in a large number of patients." (PMID 34912245, 2021). "High levels of C-reactive protein (CRP), a marker of acute inflammatory response, are independently associated with delirium." (PMID 34526093, 2021). "The NLR and CRP can be useful in elaborating existing delirium prediction models, such as the prediction of delirium in the ICU model (PRE-DELIRIC), and can also be utilized as key features in machine learning-based future prediction models." (PMID 34912245, 2021). "In particular, NLR has been reported to have higher predictive value in delirium than CRP, neutrophils, and lymphocytes." (PMID 34034650, 2021). "Of note, increased levels of NLR have been reported to have higher predictive value in delirium than CRP, neutrophils and lymphocytes." (PMID 34887744, 2021). "The NLR and CRP levels in DE increased on the day of delirium onset compared to the initial day of ICU admission." (PMID 34912245, 2021). "This study shows that changes in NLR can be more efficient in early detecting overall delirium, compared to CRP." (PMID 34912245, 2021). "There have been multiple efforts to identify the predictive markers of delirium, such as increased C-reactive protein (CRP), particularly with regard to a potential neuro-inflammatory etiology." (PMID 34140560, 2021). "As the primary outcome, we investigated serial changes of NLR and CRP during the course of delirium onset, while comparing the changes over time in non-delirium patients." (PMID 34912245, 2021). "The main effect of time was also significant as the CRP level increased in delirium onset compared to baseline in both subtypes." (PMID 34912245, 2021). "This study found that the NLR and CRP levels increased on the day of delirium onset compared to those on the initial day of ICU admission." (PMID 34912245, 2021). "And the three analysis methods yielded consistent conclusions, which to a more extent showed that there was a correlation between the rise of CRP and the occurrence of delirium." (PMID 32851079, 2020). "Both logistic and linear regression analyses showed that the increase in CRP after surgery was significantly related to the occurrence of delirium." (PMID 32851079, 2020). "The purpose of this study was to explore the relationship between the perioperative increase in CRP and delirium occurrence after operation." (PMID 32851079, 2020). "Recent work correlated markers of systemic inflammation and those of astrocyte and glial cell activation (IL-6, IL-8, IL-10, TNF-α, C-reactive protein and S-100β levels) with longer duration of delirium, more severe delirium and higher in-hospital mortality." (PMID 32443606, 2020). "Worldwide, there are several clinical studies that have explored the relationship between CRP and delirium in elderly patients or ICU settings." (PMID 32851079, 2020). "Using clinical and laboratory factors, we determined that an index composed of age, NIHSS score, neurological findings, leucocyte count, NLR, and CRP was better at predicting early-onset delirium after acute ischemic stroke than any of the factors alone." (PMID 31336587, 2019).
delirium (continued). "Accumulating evidence has disclosed that high levels of CRP are closely correlated with increased risks of POCD or postoperative delirium (POD)." (PMID 31138765, 2019). "Patients with delirium had higher CRP values at the time of HUT (median 174 [range 67–306] mg/L vs 62 mg/L; p = 0.04)." (PMID 30683068, 2019). "Patients with delirium did show lower value of hemoglobin (p = 0.002), higher inflammatory response (CRP: p = 0.01), higher rate of heart enzymes (CK: p = 0.03; CK-MB: p = 0.04), and worse kidney function (creatinine: p = 0.001)." (PMID 28560042, 2017). "C-reactive protein (CRP), one of the most common markers for systemic inflammation, has been indicated as independent risk factor for delirium following vascular surgery and hip surgery." (PMID 29181397, 2017). "Age, low physical activity, hearing impairment, heavy alcoholism, history of prior delirium, ICU admission, emergency surgery, open surgery, and increased preoperative C-reactive protein were independent predictors of postoperative delirium." (PMID 27015177, 2016). "Studies have shown that higher levels of C-reactive protein (CRP) and interleukin (IL)-6 are associated with a greater incidence of delirium in postoperative hip surgery patients." (PMID 21366899, 2011). "In vascular surgery patients, higher preoperative CRP concentrations augment the probability of postoperative delirium." (PMID 20591163, 2010). "each intervention reduces circulating concentrations of the inflammatory marker CRP; CRP concentration correlates with post-operative complications; anesthetic sensitivity predicts major and minor complications, including delirium." (PMID 20591163, 2010). "Given the observational nature of the included studies and high heterogeneity, these findings support CRP as a correlate, rather than a causal mediator, of delirium-related inflammation." (PMID 41695631, 2026). "Only a few studies employed serial sampling, which demonstrated that rising biomarker concentrations, such as CRP or NfL, may precede delirium onset, offering predictive potential." (PMID 40889075, 2025). "The Walter Index combined with delirium alone showed an optimism-corrected AUC of 0.723 (95% CI, 0.702-0.749); adding only frailty yielded an AUC of 0.713 (95% CI, 0.690-0.736), and adding only CRP level yielded an AUC of 0.716 (95% CI, 0.694-0.743)." (PMID 39841475, 2025). "The study investigated whether incorporating delirium, frailty, or C-reactive protein level enhanced accuracy." (PMID 39841475, 2025). "Furthermore, we also investigated the relationship between serum CRP levels and the severity of symptoms, drug use (opioid oral morphine, benzodiazepine, and/or psychotropic drugs), and the patients’ delirium." (PMID 41302347, 2025). "Importantly, the authors of this report also observed that a preoperative increase in C-reactive protein concentration is an independent predictor of postoperative delirium development." (PMID 41303282, 2025). "The relationship between CRP and delirium severity suggests that biochemical markers of inflammation may serve as early warning indicators of postoperative neurocognitive complications." (PMID 41303282, 2025). "Feature importance analysis revealed the following variables as the most influential in the SVM model, listed in order of importance: cerebrovascular disease, fracture, CCI, blood pH, APACHE II, CRP, MV, hemoglobin, delirium, lactate, benzodiazepines, dexmedetomidine, and head injury." (PMID 38789502, 2024). "Research by Song demonstrated a positive correlation between CRP levels and postoperative delirium." (PMID 39536046, 2024). "Given the complex etiology of delirium—encompassing inflammatory processes, polypharmacy, and chronic conditions—we integrated biomarkers such as C-reactive protein into the FI-Lab model, offering fresh perspectives for early identification and intervention in clinical practice." (PMID 39737160, 2024).
delirium (continued). "CRP is commonly used clinically as a blood biomarker also in delirium and in postoperative patients or patients with multiple traumas characterized by an early complement component 3 (C3) activation, represented by plasma C3 depletion and upregulation of cleaved forms of C3 (including C3a and C3b)." (PMID 37958765, 2023). "In peripheral blood of surgical patients, our prior work has demonstrated that delirium is characterized by higher preoperative levels of the inflammatory markers C-reactive protein (CRP) and chitinase 3-like protein-1 (CHI3L1/YKL-40), as well as a postoperative hyperactive inflammatory response." (PMID 37759795, 2023). "Interestingly, we conducted a meta-analysis with IL-6, TNF-α, and CRP, which were the most investigated biomarkers, and we found that they were statistically significant predictors of delirium." (PMID 37251808, 2023). "The results of this MR analysis did not support that peripheral TNF-α, CRP, IL-1α, IL-1β, IL-2, IL-6, sIL-6Rα, soluble gp130, and IL-8 were causally associated with delirium." (PMID 37649721, 2023). "An earlier study had indicated a potential link between delirium and the inflammatory marker CRP." (PMID 37928911, 2023). "With the aid of large-scale GWAS datasets, we did not observe any evidence that genetically elevated CRP was significantly associated with delirium." (PMID 37649721, 2023). "Similar to previous studies, we could show overall elevated CRP levels in our patients with delirium, which supports our finding of infection as the main diagnosis in our sample." (PMID 36928887, 2023). "Thus, greater postoperative concentrations of CRP are needed to develop postoperative delirium in the patients." (PMID 36212043, 2022). "Therefore, we set out to determine the effects of preoperative plasma concentration of homocysteine, the postoperative plasma concentration of CRP, and their interactions on the incidence and severity of postoperative delirium in patients." (PMID 36212043, 2022). "More importantly, the preoperative plasma concentration of homocysteine still modified the association between the postoperative plasma concentration of CRP and the incidence of postoperative delirium after adjusting the days when postoperative CRP amounts were measured." (PMID 36212043, 2022). "Thus, mild inflammation, represented by a slight increase of postoperative plasma CRP, can promote postoperative delirium." (PMID 36212043, 2022). "In conclusion, the postoperative plasma concentration of CRP, but not the preoperative plasma concentration of homocysteine, was associated with the incidence and severity of postoperative delirium." (PMID 36212043, 2022). "In our study, higher CRP values were found in patients with cardiac problems, in coincidence with the observations of other studies in which high CRP values were related to delirium in older people with acute disease and post operative delirium in heart surgery." (PMID 36013306, 2022). "Specifically, the postoperative plasma concentration of CRP was associated with the postoperative delirium incidence in the patients with lower, but not higher, preoperative plasma concentrations of homocysteine." (PMID 36212043, 2022). "Patients who developed a delirium had lower CRP levels at admission (70 [IQR 35–119] vs. 89 [IQR 40–152] mg/L p = 0.04), a higher creatinine level at admission (98 [IQR 75–134] vs. 87 μmol/L, p = 0.02), and a shorter duration of symptoms pre‐admission (5 [IQR 3–8] vs. 7 days p = 0.002)." (PMID 36052424, 2022). "To investigate the link between systemic inflammation and brain microstructural changes in COVID-19 encephalopathy patients, we studied the association between C-reactive protein (CRP) levels and ADC in nine white matter regions previously associated with delirium." (PMID 34709472, 2021). "According to the results of this study, CRP might be used as an early-recognition biomarker for hyperactive and mixed motor delirium subtypes." (PMID 34912245, 2021).
delirium (continued). "This can be interpreted as the NLR may be the more effective inflammatory marker in early detection of delirium occurrence, compared to CRP." (PMID 34912245, 2021). "Surface contact between blood and CPB instrument can induce SIRS, which may be involved in the occurrence of delirium after operation through C-reactive protein, IL-1, and IL-10." (PMID 32664963, 2020). "There are few reports on the relationship between CRP and postoperative delirium in China." (PMID 32851079, 2020). "Yet, an inadequate immune system response could play a major role in POD in cardiac surgery as it has been shown by the white blood cells differential count and the CRP increase in delirium patients." (PMID 32987655, 2020). "Future studies strengthened the relationship between frailty, CRP, and delirium." (PMID 32244301, 2020). "They found that CRP level was highly correlated with delirium occurrence." (PMID 32851079, 2020). "In older persons undergoing major non-cardiac surgery, high levels of C-reactive protein (CRP) were found to be significantly associated with higher incidence of delirium, duration, and feature severity." (PMID 32244301, 2020). "It was even documented that high CRP levels could predict the incidence and recovery of delirium in elderly patients." (PMID 32851079, 2020). "The findings of this study regarding NLR, white blood cells differential count, and CRP suggest that an inadequate response of the immune system and oxidative stress may play a role in the pathogenesis of delirium." (PMID 31336587, 2019). "Among inflammatory markers, increased procalcitonin, CRP, and IL-6 were consistently reported to be associated with delirium with the exception of one study that found no increase in IL-6 levels." (PMID 31263968, 2019). "Furthermore, the proportion of infections, mean hemoglobin concentration, BUN/Creat and CRP levels in our patients matches the anomalies reported in older adults delirium studies which suggests that our cohort reflects hospitalized older adults with delirium." (PMID 30941098, 2019). "Furthermore, albumin, TC, HDL-C, and LDL-C levels were significantly lower, whereas creatinine, CRP, and N-terminal pro-brain natriuretic peptide (NT-proBNP) levels were significantly higher in the delirium group." (PMID 30413062, 2018). "The effect of preoperative statin for prevent delirium was more dominant at the lower CRP interval." (PMID 29570715, 2018). "Similarly, patients with delirium had higher preoperative and postoperative lactate dehydrogenase (preoperative, p=0.013; postoperative, p=0.042) and postoperative C-reactive protein (p=0.011)." (PMID 30515421, 2018). "An increased CRP is an indicator for infections, which are a trigger for delirium in general." (PMID 28828209, 2017). "In patients with delirium, post-operative leucocyte counts and C-reactive protein levels were slightly but significantly higher on ICU admission, which might indicate a role of systemic inflammation in the development of delirium." (PMID 27544077, 2016). "Age, low physical activity, hearing impairment, heavy alcoholism, history of prior delirium, intensive care unit (ICU) admission, emergency surgery, open surgery, and increased preoperative C-reactive protein were identified as independent predictors of postoperative delirium." (PMID 27015177, 2016). "In addition, Zhang and colleagues recently demonstrated that C-reactive protein measured on ICU entry and its changes are associated with delirium." (PMID 24886875, 2014). "However, this timeline for development of delirium is consistent with the peak levels of inflammatory mediators in the postoperative period, such as interleukin-6 (which peaks after 24 h) and C-reactive protein (which peaks after 48 h)." (PMID 23272945, 2012).
delirium (continued). "Higher levels of procalcitonin were associated with fewer delirium/coma-free days [odds ratio (OR), 0.5; 95% confidence interval (CI), 0.3 to 1.0; P = 0.04], whereas higher CRP levels showed trends towards fewer delirium/coma-free days (OR, 0.6; 95% CI, 0.3 to 1.1; P = 0.08)." (PMID 21366899, 2011). "We assessed the role of both procalcitonin and CRP in non-brain organ dysfunctions and survival and found little evidence that the observed associations between the biomarkers and delirium/coma-free days were driven by a relationship with survival." (PMID 21366899, 2011). "Similarly, patients with a baseline CRP level of 107 mg/L (the 25th percentile) had a mean (95% CI) of 1.0 (-0.25 to 2.3) more day alive and free of delirium and coma than those with a CRP level of 281.5 mg/L (the 75th percentile)." (PMID 21366899, 2011). "The lack of association of CRP with delirium in our MR analysis suggests that previous findings from observational studies might be affected by some degree of bias, such as surgical type." (PMID 37649721, 2023). "Moreover, various CSF CRP concentrations have been noted in delirium, ALS, severe head injury, aneurysmal subarachnoid hemorrhage, CNS vasculitis and giant cell arteritis, and epilepsy, as well as in neonatal meningitis and non-meningitis systemic inflammatory responses." (PMID 37873776, 2023). "However, the data fails to show an association between elevated CRP levels and delirium severity and poorer performance in MMSE, which was indicated by previous studies but also contradicted by others." (PMID 36928887, 2023). "The postoperative plasma concentration of CRP was associated with the incidence of postoperative delirium before and after adjusting for age, sex, preoperative MMSE, and day of postoperative CRP measurement (adjusted OR per one standard deviation change in CRP: 1.51; 95% CI: 1.05–2.16; P = 0.026)." (PMID 36212043, 2022). "Moreover, we further demonstrated that the established association between the postoperative plasma concentration of CRP and the postoperative delirium incidence could be modified by the preoperative plasma concentrations of homocysteine." (PMID 36212043, 2022). "Homocysteine and C-reactive protein (CRP) may serve as biomarkers of postoperative delirium." (PMID 36212043, 2022). "Specifically, the association between postoperative blood CRP concentration and postoperative delirium occurred in patients with APOE4, but not non-APOE4, carriers, suggesting the contribution of gene-protein interaction to the development of postoperative delirium." (PMID 36212043, 2022). "However, the preoperative plasma concentration of homocysteine could modify the established association between the postoperative plasma concentration of CRP and the incidence of postoperative delirium." (PMID 36212043, 2022). "Therefore, it is questionable whether NLR is truly related to delirium and whether it is more useful than CRP." (PMID 34912245, 2021). "Therefore, the authors would like to underline that using clinical and laboratory factors combined in one score composed of age, NIHSS score, neurological findings, leucocyte count, NLR, and CRP is better at predicting early-onset delirium after acute ischemic stroke than any of the factors alone." (PMID 31336587, 2019). "The etiology of delirium might further be related to neuroinflammation, as biomarker analysis has associated an elevation of several inflammatory factors (among others, C-reactive protein, procalcitonin and IL-8) with the duration of the delirium or brain dysfunction." (PMID 27555812, 2016). "The association between CRP and delirium has been described previously in non-septic patients." (PMID 18457586, 2008). "CRP has been widely studied as a biomarker for predicting postoperative cognitive dysfunction (POCD), including delirium, particularly in older adults." (PMID 40529139, 2025).